IL25 (interleukin 25)
Diseases named in the same sentence as IL25 in open-access papers (continued):
Sharing a sentence is not in itself a finding about the gene and the disease.
inflammatory bowel disease (16 papers, 2013 to 2025). A spectrum of small and large bowel inflammatory diseases of unknown etiology. "Exogenous IL-25 was reported to suppress intestinal inflammation in animal models of inflammatory bowel diseases via suppressing IL-12 and IL-23 production." (PMID 37898756, 2023). "IL-25 is also involved in chronic inflammation from inflammatory bowel disease (IBD) and rheumatoid arthritis (RA)." (PMID 36311787, 2022). "IL-25 has been shown to skew immune responses to the Th2 phenotype and was seen to be decreased in the sera and inflamed mucus of patients diagnosed with inflammatory bowel disease (IBD)." (PMID 24454481, 2013). "The present study suggests that IL-25 may contribute to the pathogenesis of inflammatory bowel disease in at least a subgroup of patients." (PMID 25937893, 2014). "Of note, IL-25 and IL-33 have been reported to modulate the severity of various inflammatory diseases involving IL-1β secretion including allergic inflammation, autoimmunity and inflammatory bowel disease." (PMID 23935505, 2013). "One of the characteristics of inflammatory bowel disease (IBD) is a low level of IL-25, and IL-25 treatment inhibits Toll-like receptors (TLRs)-induced inflammation and further alleviates the symptoms of IBD." (PMID 36119076, 2022). "Emerging evidence highlights the tuft cell—Interleukin-25 (IL-25) axis (tuft/IL-25 axis) as a critical orchestrator bridging luminal stimuli and intestinal immunity in Inflammatory Bowel Disease (IBD), which encompasses Crohn’s Disease (CD) and Ulcerative Colitis (UC)." (PMID 41041315, 2025). "Regarding the antagonism of the two cytokines, studies have shown that in inflammatory bowel disease (IBD), TNF-α can inhibit the synthesis of IL-25, while TGF-β1 can stimulate the up-regulation of IL-25 in colon tissue." (PMID 35069596, 2021). "In addition, IL25 and IL33 are also secreted by ILC2s, mediating the fibrosis pattern in pulmonary fibrosis and raising questions regarding the stenosis inducer subset of inflammatory bowel diseases (IBD)." (PMID 33673676, 2021).
Obesity (16 papers, 2019 to 2026). Accumulation of substantial excess body fat. "Previously, we found that nematode infection stimulated type 2 immunity by releasing macrophage-responsive Th2 cytokines including interleukin (IL)-25 that modulated body weight and metabolic dysfunction associated with obesity." (PMID 34351905, 2021). "Our study indicated that the modulation of IL-25 signaling might play a potential therapeutic role against obesity and its associated metabolic disorders." (PMID 34351905, 2021). "In conclusion, the activation of IL-25 signaling in WAT may have therapeutic potential for controlling obesity and its associated metabolic disorders." (PMID 34351905, 2021). "Combined, we here demonstrated that several key metabolic parameters related to intake of HFD and diet-induced obesity associated with decreased Il25 and Tslp expression levels in small intestinal tuft cells without affecting immune homeostasis of the connected lamina propria." (PMID 34122403, 2021). "Despite the circuit, Feng reported that IL-25 promotes M2 macrophage polarization and thereby stimulates lipolysis and mitochondrial activity against obesity." (PMID 38283340, 2023). "IPA holds potential as a reagent for obesity treatment due to its ability to activate TCs and promote IL-25 production." (PMID 38283340, 2023). "While IL-25 mainly protects from obesity by stimulating M2 macrophages and inducing lipolysis, TSLP acts trough activation of DCs to prime naïve T cells for differentiation into Th2 cells." (PMID 35844529, 2022). "Previous studies showed that IL-25 promoted lipid metabolism, thereby fighting against obesity, improved glucose tolerance in obese mice and helped to maintain glucose homeostasis." (PMID 35126394, 2022). "Mice fed with a high-fat diet (HFD) were protected from obesity and related metabolic disorders when given IL-25 through a process that involved the uncoupling protein 1 (UCP1)-mediated thermogenesis." (PMID 34351905, 2021). "We found IL11RA and IL17RB were downregulated, IL19 and IL25 were upregulated in obesity group compared with normal group." (PMID 33197880, 2020). "Our previous studies had clearly indicated that M2 macrophages induced by IL-25 alleviated obesity and NAFLD." (PMID 31296243, 2019). "IL-25 plays a vital role in diabetes by preserving gut barrier integrity by promoting tuft cell expansion and IL-25 secretion, potentially through the free fatty acid receptor 3 pathway, which helps prevent obesity and metabolic disorders." (PMID 40536951, 2026). "IL-25 also plays a role in inflammatory diseases including obesity and digestive system disorders." (PMID 37005677, 2023). "Reduced levels of TC-secreted IL-25 may be linked to IBD, obesity, duodenal ulcer, and acute duodenitis." (PMID 36704202, 2022). "IL-25 stimulated macrophages to polarize toward the M2 phenotype, promoted lipid metabolism by regulating the expression of lipolytic and lipogenic enzymes and improving mitochondrial respiratory capacity, thereby against obesity." (PMID 35126394, 2022). "Furthermore, we investigated the source of IL-33 and IL-25 responsible for ILC2 activation in the context of a chronic low-grade inflammation such as diet-induced obesity and metabolic syndrome." (PMID 30755607, 2019). "This may provide solution for obesity by modulating TC secretion of IL-25 and TLSP." (PMID 36704202, 2022). "Obesity affects allergic airway inflammation through mast cell influx and the release of TSLP and IL-25." (PMID 36051916, 2022). "Thus, intervention targets on TCs, ILC2s or the circuit including IL-25, IPA, berberine and succinate, dramatically reduced the obesity status." (PMID 38283340, 2023). "In recent years, also other alarmins, such as IL-25 and thymic stromal lymphopoietin (TSLP), have been investigated and, for both, a supporting role on the Th2 response and protective effect against obesity could be shown." (PMID 35844529, 2022).
Obesity (continued). "However, this circuit is disrupted and downregulated IL-25 and TSLP marked TCs in obesity." (PMID 38283340, 2023). "To investigate whether IL-25 regulates its anti-obesity and antidiabetic effects through macrophages, we injected mice with DIO with clodronate-loaded liposomes to deplete macrophages in adipose tissue and also injected IL-25." (PMID 34351905, 2021). "Genetic ablation of UCP1 may not influence the IL-25–mediated anti-obesity effect because IL-25 reduced body weight gain and eWAT mass, lowered liver mass in obese UCP1+/+ as effectively as in obese UCP1−/− mice." (PMID 34351905, 2021). "However, IL-25 injection could reduce body weight gain and eWAT mass, lower liver weight in mice with DIO that were injected with clodronate-loaded liposomes, suggesting that macrophages are not necessary for all of the anti-obesity effects activated by IL-25." (PMID 34351905, 2021).
COVID-19 (15 papers, 2020 to 2024). A disease caused by infection with severe acute respiratory syndrome coronavirus 2. "IL-33, TSLP, and IL-25 have been implicated as potential predictors of severe COVID-19 outcomes, associated with severe lung inflammation, making them promising candidates for disease severity control." (PMID 37761861, 2023). "It is known that IL-25 is produced by epithelial tuft cells (and possibly other cells) in response to cell damage, whereas low absolute and relative basophil counts have been associated with a high risk of developing severe COVID-19, SARS, and MERS coronavirus infections." (PMID 36012146, 2022). "The ELF concentrations of IL-6, IL-8, IL-17A, IL-25, and IL-31 were significantly increased in COVID-19 patients." (PMID 38654351, 2024). "Significantly higher levels of total IL-33 and IL-25 were measured in the serum of COVID-19-positive patients compared to COVID-19-negative individuals." (PMID 37761861, 2023). "So, the current study evaluated the cardiac biomarkers and expression analysis of IL-1, IL-6, IL-10, IL-17 and IL-25 among COVID-19 patients from Pakistan." (PMID 36298704, 2022). "A hyper-regulation of IL-17E, also known as IL-25, among COVID-19 patients was observed in the current study, produced by all epithelial cells." (PMID 36298704, 2022). "The concentration of alarmin cytokines IL-33, TSLP, and IL-25 were compared in COVID-19-positive and -negative patients, and the association of alarmin cytokine levels with disease severity and age-related variations was evaluated." (PMID 37761861, 2023). "Besides its new role in COVID-19 patients, the IL-25 possesses unique structures and can regulate immune and inflammatory responses and angiogenesis." (PMID 36298704, 2022). "A total of 500 COVID-19 patients with elevated cardiac biomarkers were studied for the analysis of myocardial abnormality through cardiac enzymes, inflammatory biomarkers, and the expression analysis of various cytokines, including IL-1, IL-6, IL-10, IL-17, and IL-25 genes." (PMID 36298704, 2022). "This study provides novel insights into the role of alarmin cytokines, specifically IL-33, IL-25, and TSLP, in COVID-19." (PMID 37761861, 2023). "Overall, our findings suggest that alarmin cytokines (IL-33, TSLP, and IL-25) could serve as potential therapeutic targets to modulate disease severity in COVID-19, and genetic variations influencing protein production can also protect against developing severe COVID-19." (PMID 37761861, 2023). "Compared with those in healthy volunteers, the concentrations of interleukin (IL)-6 (median 27.6 pmol/L), IL-8 (1045.1 pmol/L), IL-17A (0.8 pmol/L), IL-25 (1.5 pmol/L), and IL-31 (42.3 pmol/L) were significantly greater in the ELF of COVID-19 patients than in that of volunteers." (PMID 38654351, 2024). "They observed that IL25 was significantly elevated in COVID-19 patients, though specific findings related to IL-25 and its contribution to the COVID-19 inflammatory response or to mortality were not discussed." (PMID 37631998, 2023). "We also observed significantly elevated levels of IL-33 and IL-25 proteins in COVID-19 patients compared to non-COVID individuals." (PMID 37761861, 2023). "However, they also identified alarmins, such as IL-25, IL-33, and TSLP, which they suggested were likely to contribute to lung inflammation during different phases of disease progression in COVID-19." (PMID 37631998, 2023). "Similarly, FGF-2, FLT-3L, IL-9, IL-17E/IL-25, IP-10, MCP-3, and MIP-1β were also positively correlated with SOFA scores in COVID-19 patients." (PMID 34131192, 2021).
autoimmune disease (14 papers, 2016 to 2026). A disorder resulting from loss of function or tissue destruction of an organ or multiple organs, arising from humoral or cellular immune responses of the individual to their own tissue constituents. "Epithelium-derived cytokines, such as IL-33, IL-25, and thymic stromal lymphopoietin are alarmins that are involved with type-2, type-1, and type-17 immune responses, and are associated with autoimmune diseases and allergic disorders." (PMID 39214920, 2024). "These responses culminate in the production of a plethora of cytokines such as TSLP, IL-9, IL-25, and IL-33, which have been implicated in the pathogenesis of several inflammatory and autoimmune diseases." (PMID 37063828, 2023). "In autoimmune diseases, IL-25 is elevated and associated with an increased level of autoantibodies in the peripheral blood of patients." (PMID 37005677, 2023). "With their expression by barrier epithelial cells, the cytokines interleukin-25 (IL-25) and IL-33 play key roles in intestinal immune responses, and have been associated with inappropriate allergic reactions, autoimmune diseases and cancer pathology." (PMID 36263033, 2022). "During intracellular infections, Th17-mediated immunity (often associated with autoimmune diseases) has also been shown to be activated, bridging and modulating both the Th1 and Th2 responses by IL-25 (also known as IL-17E)." (PMID 35071039, 2021). "Studies suggest that, like TSLP, IL-25 plays a dual role in regulating the immune response during the development of autoimmune diseases." (PMID 40981017, 2025). "It has been shown that IL-25 exacerbates autoimmune disease progression in many mice models, including SS and IBD." (PMID 37005677, 2023). "IL-25 is involved in a variety of diseases (cancer, inflammation, and autoimmune diseases), so IL-25 has potential in explaining disease pathways, drug/disease interactions, and offering reference for associated research of clinical treatment." (PMID 37005677, 2023). "In particular, the following chapters focus on the mode of action and mechanisms of IL-25 in various cancers, cascade inflammation triggered by type 2 immune response, and autoimmune diseases." (PMID 37005677, 2023). "Previous studies have suggested a strong relationship between IL-25 and cancer, inflammation, and autoimmune diseases." (PMID 37005677, 2023). "This review presents current evidence on the roles of IL-25 in cancers, allergic disorders, and autoimmune diseases." (PMID 37005677, 2023). "Here, we review recent advances in the roles of IL-25 in the pathogenesis of inflammation and autoimmune diseases." (PMID 34122457, 2021). "The current studies show that IL-25 not only plays an important role in the regulation of type 2 immune responses and inflammatory, skin, and autoimmune diseases but also has a certain role in the treatment of tumors." (PMID 30345318, 2018). "IL-25 is actively involved in the progression and prognosis of autoimmune diseases." (PMID 37005677, 2023). "Although IL-25 (originally termed IL-17E) shares structural similarity with other IL-17 family members it acts in an opposing manner to IL-17A, by inducing a suite of Type 2 responses and preventing IL-17A-dependent autoimmune disease." (PMID 30238872, 2018). "Although the molecular mechanism of IL-25 in autoimmune disease remains unknown, previous studies, as well as the data reported herein, show that IL-25 strongly induced type 2 cytokines, such as IL-4 and IL-1330, 31, which are potent CIA inhibitors." (PMID 27812008, 2016). "Therefore, it should be consider the immunological status of the patient and progression of the autoimmune disorder in determining the potential clinical utility of IL-25." (PMID 27812008, 2016).
hepatocellular carcinoma (13 papers, 2016 to 2026). A malignant tumor that arises from hepatocytes. "IL-25 was detected in hepatocellular carcinoma (HCC), colorectal cancer (CRC), gastric cancer, oral squamous epithelial cell carcinoma, and multiple myeloma at a higher level compared to that of healthy individuals." (PMID 37005677, 2023). "The mechanisms behind these effects are not fully understood, but some researchers believe that IL-25-induced dysregulation of intestinal microbiota promotes hepatocellular carcinoma through alternate activation of macrophages in the tumor microenvironment." (PMID 36119529, 2022). "It was uncovered that the alternative activation of macrophages induced by IL-25 promoted the migration, invasion and tumorigenesis of hepatoma cells, increased the expression of vimentin, Snail and phospho-ERK, and decreased the expression of E-cadherin in hepatoma cells." (PMID 38818476, 2024). "Current results indicate a significant role of IL-33 in liver inflammation and fibrosis progress in CHC, whereas IL-17 and IL-25 may be used as biomarkers for the development of hepatocellular carcinoma." (PMID 35056005, 2022). "The results indicate a possibility of the use of IL-33 as a biomarker for liver fibrosis progress in patients suffering from CHC, whereas IL-17 and IL-25 could be used as biomarkers for the development of hepatocellular carcinoma." (PMID 35056005, 2022). "In terms of dysbiosis-mediated metabolic rewiring of the innate immune system, microbiome imbalance favors hepatocellular carcinoma (HCC) development via IL-25-facilitated alternative activation of TAMs." (PMID 41557725, 2026). "In hepatocellular carcinoma (HCC) patients with HBV history, interleukin-25 (IL-25) is identified as a potential biomarker for lung metastasis." (PMID 39125732, 2024). "However, it was found hyperplastic epithelial tuft cells in the colon induced by gut microbiota dysbiosis might partly be the source of IL-25 and increased IL-25 promoted the progression of hepatocellular carcinoma (HCC) via alternative activation of macrophages in the tumor microenvironment." (PMID 36569325, 2022). "In this study, the role of interleukins IL-33, IL-17, and IL-25 in HCV patients and progression of disease from chronicity to hepatocellular carcinoma will be characterized in order to use them as biomarkers of disease progression." (PMID 35056005, 2022). "Current studies highlight the role of the IL-33, IL-17, and IL-25 in the pathogenesis of HCV and its progression to hepatic carcinoma." (PMID 35056005, 2022). "Finally, limited evidence suggests that DCLK1-expressing intestinal TCs in the gut can promote tumor progression in hepatocellular carcinoma (HCC) through activating alternative macrophages in tumor microenvironment via secreting IL-25." (PMID 33348546, 2020). "In the present study, the serum levels of IL-33, IL-17 and IL-25 were determined in patients with chronic hepatitis C (CHC) and hepatocellular carcinoma (HCC) and compared to healthy controls (C)." (PMID 35056005, 2022). "Moreover, IL25 could promote proliferation and sustain self-renewal of NANOG positive hepatocellular carcinoma by activating NF-κB and JAK/Stat3 pathways." (PMID 35359953, 2022). "IL-25 has been found to activate M2 TAMs, induce the expression of chemokine CXCL10, and promote epithelial-mesenchymal transition (EMT) in hepatocellular carcinoma (HCC), thereby facilitating tumor progression and metastasis." (PMID 38835386, 2024).